SNORD11 (small nucleolar RNA, C/D box 11)
Synonyms: HBII-95
Gene: Small nucleolar RNA gene on chromosome 2 (202,293,051 to 202,293,134, forward strand). Ensembl gene ENSG00000238317.
Gene Ontology:
Biological process: RNA processing
Cellular component: nucleolus
Homologues: Orthologues: macaque SNORD11 (100% identical), mouse Snord11 (87% identical), rat Snord11 (87% identical).
Diseases named in the same sentence as SNORD11 in open-access papers:
SNORD11 is named in the same sentence as 3 diseases in open-access papers, as found by Europe PMC text mining. Sharing a sentence is not in itself a finding about the gene and the disease. The quoted sentences say what the papers report.
tumor (1 paper, 2022). "We identified 42 DEs and established 6 survival-related snoRNAs using Cox analysis: 2 of the 6 snoRNAs, SNORA16B and SNORD63, are protective factors, and the other 4 (SNORA59B, SNORD11, SNORD46, and SNORD 124) are risk factors that may play a crucial role in tumor metastasis and progression." (PMID 36181013, 2022).
SNORD11 also shares sentences with these, for which no sentence is quoted: cancer (1 paper); Sepsis (1).